SLC22A3 (solute carrier family 22 member 3)
Diseases named in the same sentence as SLC22A3 in open-access papers (continued):
Sharing a sentence is not in itself a finding about the gene and the disease.
pancreatic cancer (5 papers, 2017 to 2023). "The present study shows for the first time that the protein presence and to some extent also localization of SLC22A3 significantly associate with prognosis of pancreatic cancer in both unstratified and chemotherapy-treated patients." (PMID 31874997, 2019). "Protein localization and brush border staining intensity of ABCC2 and SLC22A3 was assessed in tumor tissue blocks of 65 pancreatic cancer patients and associated with clinical data and survival of patients with regard to therapy." (PMID 31874997, 2019). "Expression of the solute carrier (SLC) transporter SLC22A3 gene is associated with overall survival of pancreatic cancer patients." (PMID 28272475, 2017). "The rs2504938 SNP in SLC22A3 significantly associates with an unfavorable prognosis of pancreatic cancer patients." (PMID 28272475, 2017). "This study tested the hypothesis that genetic variation in the SLC22A3 gene contributes to pancreatic cancer risk and disease survival." (PMID 28272475, 2017). "This study tested whether genetic variability in SLC22A3 associates with pancreatic cancer risk and prognosis." (PMID 28272475, 2017). "This study investigated significance of protein expression and cellular localization of the previously suggested putative prognostic markers ABCC2 and SLC22A3 in pancreatic cancer patients." (PMID 31874997, 2019). "Negative SLC22A3 brush border staining in pancreatic tumors significantly increased the risk of both disease progression and patient ́s death in univariate analyses." (PMID 31874997, 2019). "In conclusion, common variation in the SLC22A3 gene is unlikely to significantly contribute to pancreatic cancer risk." (PMID 28272475, 2017). "Through PPI construction, we identified several genes, including mRNA (CAP2, SLC22A3), miRNA (miR-9985, miR-27, miR-548), and TFs (CEBPA), involved in the prognosis mechanism of pancreatic cancer." (PMID 37857015, 2023). "In pancreatic cancer patients, overexpression of ABCC2 along with SLC22A3 in a combination was detected." (PMID 33865438, 2021). "The SLC22A3 and CAP2 might become specific predictive signatures for diagnosing pancreatic cancer." (PMID 37857015, 2023). "Role of protein expression of SLC22A3 in pancreatic cancer was not addressed to date." (PMID 31874997, 2019).
diabetic nephropathy (3 papers, 2020 to 2023). "In a study of unrelated Finnish patients with T1DM, an association was found between SLC22A3 rs2048327 and diabetic nephropathy (DN) in men (p < 0.03)." (PMID 37626799, 2023). "SLC22A3 encodes an organic cation transporter with diabetic nephropathy and hypertension with a broader pattern of expression including the small intestine, liver, kidney, placenta, skeletal muscle, heart and brain." (PMID 34143809, 2021).
head and neck squamous cell carcinoma (3 papers, 2017 to 2021). A squamous cell carcinoma that arises from any of the following anatomic sites: lip and oral cavity, nasal cavity, paranasal sinuses, pharynx, larynx, and salivary glands. "This study investigated whether SLC22A3 expression is related to cisplatin uptake and the survival of patients with head and neck squamous cell carcinoma (HNSCC)." (PMID 29088791, 2017).
Obesity (3 papers, 2020 to 2025). Accumulation of substantial excess body fat. "The first model included genetic variants known to be associated with obesity—specifically, ADCY3 rs11676272, CLOCK rs1801260, GPR61 rs41279738, FTO rs1421085, RP11-775H9.2 rs1296328, SLC22A3 rs9364554, and TFAP2B rs734597—and explained 8.3% of the variance in BMI." (PMID 39766774, 2024). "Previous GWASs have demonstrated the association of the studied polymorphic loci ADCY3 rs1167627272, CLOCK rs1801260, FTO rs1421085, GPR61 rs41279738, RP11-775H9.2 rs1296328, SLC22A3 rs9364554, and TFAP2B rs734597 with obesity-related phenotypes." (PMID 39766774, 2024).
hyperglycaemia (2 papers, 2017 to 2020). "Higher DNA methylation of SLC22A3 could be a potential mechanism to decrease expression of this gene, leading to reduced antidiabetic effects of metformin resulting in hyperglycaemia." (PMID 28947922, 2017).
acute promyelocytic leukemia (1 paper, 2022). An aggressive form of acute myeloid leukemia (AML), characterized by arrest of leukocyte differentiation at the promyelocyte stage, due to a specific chromosomal translocation t(15;17) in myeloid cells. "Kaplan–Meier analysis showed that high expression of SLC22A3 predicted longer overall survival (OS) and disease-free survival (DFS) in both non-acute promyelocytic leukemia (APL) AML (non-APL AML) (P = 0.008 and 0.002) and cytogenetically normal AML (CN-AML) patients (P = 0.006 and 0.005)." (PMID 36461046, 2022).
atherosclerosis (1 paper, 2022). A disease characterized by the build-up of fatty material and calcium deposition in the arterial wall resulting in partial or complete occlusion of the arterial lumen. "In GSE20129 dataset, CARTPT, RYR2, CNTN4, PDZRN3, and SLC22A3 all showed differential expression levels in atherosclerosis vs. nonatherosclerotic samples." (PMID 35915606, 2022).
cholangiocellular carcinoma (1 paper, 2023). "In addition, a low OCT3/SLC22A3 expression was found in hepatocellular carcinoma (on protein level) and in cholangiocellular carcinoma (on the protein and mRNA levels)." (PMID 36839686, 2023).
coronary stenosis (1 paper, 2023). Narrowing of the coronary artery lumen diameter. "Similar to the previous study, in a study on the Pakistani population, with 663 subjects of whom 78% were male, SLC22A3/rs2048327 showed an association with coronary stenosis (p < 0.045) in an additive genetic model." (PMID 37626799, 2023).
familial hypercholesterolemia (1 paper, 2021). An inheritable form of hyperlipidemia, in which there are excess lipids in the blood. "Previous studies showed that the SLC22A3 rs2048327 SNP was significantly associated with cardiovascular disease events in familial hypercholesterolemia subjects." (PMID 34458338, 2021).
hyperlipidemia (1 paper, 2021). "The association between the SYTL3 and SLC22A3 polymorphisms and hyperlipidemia in the Han and Maonan groups." (PMID 34367243, 2021). "Association between the haplotypes among four SNPs of the SYTL3 and two SNPs of the SLC22A3 and hyperlipidemia in the Han and Maonan group [n (frequency)]." (PMID 34367243, 2021).
intestinal tumors (1 paper, 2020). "Several studies have suggested that OCT3 levels (SLC22A3) are reduced in intestinal tumors, which may be involved in the lack of response found in clinical practice in the treatment of other digestive tumors using irinotecan, cisplatin, and several TKIs, such as imatinib." (PMID 32933095, 2020).
leukemia (1 paper, 2022). A malignant (clonal) hematologic disorder, involving hematopoietic stem cells and characterized by the presence of primitive or atypical myeloid or lymphoid cells in the bone marrow and the blood. "Demethylation drug 5-aza-2′-deoxycytidine (DAC) activated transcription and increased mRNA expression of SLC22A3 in leukemia cell lines and AML fresh BMMNCs." (PMID 36461046, 2022). "Kaplan–Meier analysis indicated tendencies of shorter OS and leukemia-free survival (LFS) in CN-AML patients with SLC22A3 hypermethylation (P = 0.109 and 0.057)." (PMID 36461046, 2022). "The SLC22A3 post-intervention experiments confirmed that SLC22A3 downregulation led to active proliferation and diminished apoptosis of leukemia cells." (PMID 36461046, 2022). "DNA methylation and mRNA expression levels of SLC22A3 were performed on six leukemia cell lines." (PMID 36461046, 2022). "Knockdown of SLC22A3 in leukemia cells enhanced cell proliferation and suppressed cell apoptosis." (PMID 36461046, 2022). "Besides, SLC22A3 methylation pattern was irregularly distributed among leukemia subtypes (FAB)." (PMID 36461046, 2022).
liver disease (1 paper, 2020). "Downregulation of OCT1 and OCT3 (SLC22A3) was observed in HCC which was further associated with a poor survival in patients treated with sorafenib, independently from the clinical staging of the associated liver disease." (PMID 32549224, 2020).
lymph node metastasis (1 paper, 2019). "Multivariate analysis adjusted to resection margins and lymph node metastasis confirmed that the negative SLC22A3 IHC brush border staining presents high risk factor for disease progression (PFS) (P = 0.049, hazard ratio = 2.3, 95% confidence interval = 1.0–5.1), but not for death (OS)." (PMID 31874997, 2019).
melanoma (1 paper, 2018). A malignant, usually aggressive tumor composed of atypical, neoplastic melanocytes. "We demonstrate similar findings in vitro wherein knockdown of SLC22A16 in melanoma cells led to increased expression of SLC22A1 and SLC22A3." (PMID 30518936, 2018).
metastatic prostate carcinoma (1 paper, 2025). A carcinoma that arises from the prostate gland and has spread to other anatomic sites. "Indeed, the TCGA and other datasets demonstrated that SLC22A3 is downregulated in tumor tissue samples compared with normal compartments, and it is significantly diminished in castration-resistant metastatic prostate cancers." (PMID 39858458, 2025).
metastatic tumors (1 paper, 2017). "We speculate that when the expression of SLC22A3 is increased in recurrent or metastatic tumors, these tumors may become platinum-resistant." (PMID 29088791, 2017). "In our study, we enrolled only primary tumor and excluded the recurrent and metastatic tumors, therefore we have no direct evidence to know the changes of SLC22A3 expression occurring in recurrent tumors or metastatic tumors vs. primary tumors." (PMID 29088791, 2017).
ovarian carcinoma (1 paper, 2020). A malignant neoplasm originating from the surface ovarian epithelium. "In the present study, hsa_circ_0078607, which derived from the SLC22A3 gene, was significantly decreased in ovarian cancer tissues, and the biological functions of circ_0078607 was further investigated." (PMID 32503653, 2020). "Expression of SLC22A3 in ovarian cancer tissues was significantly lower than that in adjacent non-cancerous tissues." (PMID 32503653, 2020). "We also detected expression of linear SLC22A3 mRNA, which is the linear isomer of circ_0078607 in 20 selected ovarian cancer and adjacent non-cancerous tissues." (PMID 32503653, 2020).
Stroke (1 paper, 2020). Sudden impairment of blood flow to a part of the brain due to occlusion or rupture of an artery to the brain. "In female patients, 12 of the 34 SVD-associated genes were unique to that stroke cause, including FGA, SLC22A3, both unique to the female cohort, and SLC4A1 which was also expressed in males, though by different exons and junctions." (PMID 33193047, 2020).
cancer (20 papers, 2009 to 2025). A tumor composed of atypical neoplastic, often pleomorphic cells that invade other tissues. "Second, SLC22A3 function as uptake transporter of number of chemicals including antineoplastic drugs was implicated in cancer treatment efficacy and individualization." (PMID 31874997, 2019). "Taken together previous studies suggested that genetic, epigenetic or phenotypic nature of SLC22A3 can serve as putative risk predictive or prognostic biomarker in cancer." (PMID 31874997, 2019). "In addition to Fos, some other genes associatedwith cancer, such as Anxa1, Samd9, Tppp3, Slc22a3, and Ly6d, were differently regulated in both or one of the GX-rich groups,compared with the control group." (PMID 38343302, 2024). "However, although the overexpression of SLC22A3 is related to the high mortality risk of CC patients, its expression levels in normal cervical cells are dramatically higher than those in cancer patients." (PMID 36354693, 2022). "Previous authors have therefore proposed that suppression of SLC22A3 may be implicated in the progression of this cancer type." (PMID 31891614, 2019). "Gene SLC22A3 may explain clinically the differentiation associated with the high grade cancer compared with low grade cancer." (PMID 20025723, 2009). "Considering the importance of SLC22A3 in drug efficacy, this finding highlights the importance of enhancing SLC22A3 expression in combination with other anti-cancer drug in treating CRPC and NEPC patients." (PMID 39858458, 2025). "To date, many research works have indicated the association between SLC22A3 and cancers, including tumorigenesis, tumor invasion and metastasis, uptake and metabolism of antineoplastic drugs, and disease prognosis, but the significance of SLC22A3 in AML remains unclear so far." (PMID 36461046, 2022). "We also hope to identify the activators of SLC22A3 expression to enhance the uptake of cisplatin by cancer cells." (PMID 29088791, 2017). "For example, metformin, a novel drug candidate for cancer prevention, is proved to inhibit mTOR signaling, and low expression of organic cation transporter 3 (OCT3/SLC22A3), a metformin uptake transporter causes resistance to metformin." (PMID 28822012, 2017). "The metabolic pathway gene set involves genes in metabolic processes, illustrating how SLC22A3 might alter metabolic pathways within cancer cells." (PMID 39346905, 2024). "The current view about role of SLC22A3 in cancer has two aspects." (PMID 31874997, 2019). "First, SLC22A3 expression was previously connected with onset and progression of several cancers." (PMID 31874997, 2019). "We hypothesized that higher SLC22A3 expression in cancer cells may enhance the uptake of cisplatin after cisplatin treatment and, in turn, reduce the survival of cancer cells, and the opposite may hold true for cancer cells with lower SLC22A3 expression." (PMID 29088791, 2017). "In conclusion, the study findings suggest that cisplatin-induced cytotoxicity is mediated by the uptake of cisplatin by cancer cells through SLC22A3, and SLC22A3 expression in cancer cells is a potential biomarker for including cisplatin in cancer chemotherapy." (PMID 29088791, 2017). "In addition, platinum-based chemotherapeutic agents such as oxaliplatin had been reported to be substrates for SLC22A1-3, and high expression of SLC22A3 promoted the uptake of oxaliplatin, which accumulated more platinum and exerted stronger toxic effects on cancer cells." (PMID 40108724, 2025). "We also observed several genes that have been reported to change the editing level in cancer and even drive early tumor invasion and metastasis, including FLNB, SLC22A3, and AZIN1, which had significantly different editing levels in PDAC." (PMID 36895481, 2023). "Two of the identified genes (SLC22A3 and CASP2) were previously shown to be inversely correlated with cancer progression." (PMID 33509203, 2021).
cancer (continued). "This integrated analysis underscores the significant role of SLC22A3 in the immune contexture of CRC, providing valuable insights into its potential interactions with the tumor microenvironment and its implications for cancer immunotherapy." (PMID 39346905, 2024). "The presence of an altered loop in each of the genes individually (except SLC22A3) was not statistically significant in predicting cancer." (PMID 33509203, 2021). "hSLC22A3-mediated oxaliplatin uptake in cancer is thought to be important for its cytotoxicity, but it is not clear whether SLC22A3 mediated the uptake of DAC." (PMID 36461046, 2022). "Collectively, the present study and previous reports suggest that SLC22A3 may serve as a putative prognostic and predictive biomarker for follow up validation and functional studies aimed at personalized therapy of PDAC and several other, mostly gastrointestinal, cancers." (PMID 31874997, 2019).
tumor (17 papers, 2011 to 2025). "These scatter plots provide insights into how SLC22A3 expression is associated with the presence and activity of specific immune cell types within the tumor microenvironment." (PMID 39346905, 2024). "Significant correlations are indicated with asterisks, providing insights into how SLC22A3 expression is associated with genes that suppress immune responses, which can affect tumor escape mechanisms and resistance to immunotherapy." (PMID 39346905, 2024). "SLC22A3 is significantly downregulated and associated with tumor progression and worse prognosis in a variety of solid tumors." (PMID 36461046, 2022). "The analysis from TCGA and other datasets demonstrate that SLC22A3 is downregulated in tumor tissues compared to normal tissues and is further significantly diminished in CRPC." (PMID 39858458, 2025). "This nomogram provides a visual tool for estimating the probability of 1-year, 3-year, and 5-year survival rates based on cumulative scores derived from multiple prognostic factors, such as SLC22A3 expression, age, gender, and tumor stage." (PMID 39346905, 2024). "Significant correlations are marked with asterisks, highlighting the relationship between SLC22A3 expression and genes involved in activating the immune response, which can influence tumor immunogenicity and the effectiveness of immunotherapies." (PMID 39346905, 2024). "Significant correlations are marked with asterisks, highlighting the relationship between SLC22A3 expression and genes involved in chemokine receptor signaling, which plays a crucial role in immune cell trafficking and tumor microenvironment modulation." (PMID 39346905, 2024). "Higher SLC22A3 expression was also observed in patients with elevated carcinoembryonic antigen (CEA) levels, suggesting its association with tumor burden." (PMID 39346905, 2024). "By integrating these correlation analyses with references to established gene sets, this study highlights the intricate molecular interactions involving SLC22A3 and underscores its potential role as a key player in the tumor microenvironment of CRC." (PMID 39346905, 2024). "The risk factor plot illustrates the hazard ratios (HR) and confidence intervals (CI) for various clinical and molecular factors, including SLC22A3 expression, age, gender, and tumor stage." (PMID 39346905, 2024). "SLC22A3 exhibited significant differences in expression between pathological T and N stages, suggesting its involvement in tumor progression." (PMID 39346905, 2024). "RNA editing of SLC22A3 regulated by ADARB1 promotes tumor invasion and metastasis in early familial esophageal carcinoma." (PMID 35004651, 2021). "Present study demonstrates that patients with detectable SLC22A3 brush border IHC staining in their tumor cells have significantly longer OS and PFS than those without it." (PMID 31874997, 2019). "The lower SLC22A3 expression group was defined as a score difference of 0, which implies the same level of SLC22A3 expression in tumorous and adjacent normal tissues." (PMID 29088791, 2017). "Compared to TST SLC22A1 mRNA was in average 2,3-fold (± 1,4-fold) down-regulated in tumor tissue of most HCCs, whereas downregulation of SLC22A3 mRNA was lower (1,2-fold (± 1,2-fold))." (PMID 22439694, 2012). "Significant correlations are indicated with asterisks (*p < 0.05, **p < 0.01, ***p < 0.001), providing insights into how SLC22A3 expression correlates with the expression of various chemokines, which play crucial roles in immune cell recruitment and migration within the tumor microenvironment." (PMID 39346905, 2024). "These pathways are integral to tumor growth, metastasis, and the tumor microenvironment, implying that SLC22A3 may modulate these processes in CRC." (PMID 39346905, 2024). "The cell cycle regulation gene set comprises genes that control cell cycle progression and division, highlighting potential mechanisms through which SLC22A3 may influence tumor growth." (PMID 39346905, 2024).